IDH2 (isocitrate dehydrogenase (NADP(+)) 2)
Diseases named in the same sentence as IDH2 in open-access papers (continued):
Sharing a sentence is not in itself a finding about the gene and the disease.
glioma (continued). "In particular, isocitrate dehydrogenase 1 and 2 (IDH1 and IDH2) mutation and 1p/19q codeletion have been recognized as promising predictive molecular markers, resulting in their inclusion in the 2016 World Health Organization (WHO) classification of gliomas." (PMID 35053475, 2022). "For instance, under hypoxic conditions, decreased reductive glutamine metabolism was only found in gliomas with IDH1 mutations but not IDH2 mutations." (PMID 36295820, 2022). "For instance, analysis of 2-HG by proton MRS is shown to correlate with either IDH1 or IDH2 mutations in the tumor, suggesting that elevated 2-HG levels in IDH-mutated gliomas may one day offer crucial diagnostic and prognostic data." (PMID 36654821, 2022). "In addition, this study identified novel methylation loci associated with glioma CIMP that have the potential to refine the utility of WGMA assessment to detect CIMP and predict IDH1/IDH2 mutation status." (PMID 36360312, 2022). "IDH2 is often considered to have a similar prognostic effect to IDH1 in glioma." (PMID 35812244, 2022). "IDH1 and IDH2 mutations have been co-targeted though molecules such as AG-881, which is currently being evaluated in the phase 3 INDIGO trial (NCT04164901) in patients with residual or recurrent Grade 2 glioma with an IDH1 or IDH2 mutation." (PMID 34222022, 2021). "Within low-grade gliomas and secondary glioblastoma, 2HG is often produced due to mutations in the catalytic domains of isocitrate dehydrogenase isoform 1 (IDH1) and isocitrate dehydrogenase isoform 2 (IDH2)." (PMID 34222022, 2021). "Having found a high frequency of IDH1 and IDH2 mutations in subtypes of gliomas, we hypothesised role in long-term follow-up studies, finding that both IDH1 and IDH2 mutations are strong prognostic factors, supporting other data." (PMID 35996504, 2021). "Diffuse gliomas corresponding histologically to WHO grade 2 or 3 that are immunohistochemically negative for IDH1 R132H should be sequenced for less common IDH1 and for IDH2 mutations." (PMID 33293629, 2021). "Although they were thought to be virtually exclusive in glioma, further mutational analyses revealed IDH1 and IDH2 mutations, as well as IDH2 Arg140 mutations, in various cancer types such as myeloid neoplasia, chondrosarcoma, cholangiocarcinoma, and prostate cancer." (PMID 34440884, 2021). "Although H3K27me3 expression was significantly different between IDH1 and IDH2 Mut 1p/19q codeleted oligodendroglioma, the cluster patterns were not different among non-oligo gliomas regardless of IDH mutation type." (PMID 34020723, 2021). "A previous study performed a meta-analysis of IDH1 and IDH2 mutations from 55 different studies with 9,487 glioma tumors found both mutations were independently and statistically significantly associated with better OS and PFS of glioma patients." (PMID 35996504, 2021). "Finally, because 80% of LGGs harbor IDH1 or IDH2 mono-allelic mutations, secondary GBMs (GBMs arising from previous LGGs) were often thought to be virtually always IDH mutant lower grade gliomas." (PMID 33673104, 2021). "Further analyses of 923 gliomas revealed 34 and 1% of IDH1 and IDH2 mutations, respectively." (PMID 35996504, 2021). "Therefore, although both IDH1 and IDH2 mutations are rare events in human cancer, the prevalence of IDH1 mutation in lower-grade glioma suggests a tissue-specific role in tumorigenesis." (PMID 34440884, 2021). "It should also be noted that we did not investigate a model of mutant IDH2, which is a much less common mutation in glioma." (PMID 32754276, 2020). "Oligodendrogliomas are now defined as an infiltrating glioma with the presence of mutation in either IDH1 or IDH2 and co-deletion of chromosomes 1p and 19q, regardless of other histologic features." (PMID 32640746, 2020).
glioma (continued). "Among the 124 gliomas, 35.5% (44/124) had a IDH1 mutation, of which 97.7% (43/44) was R132H, and 2.3% (1/44) was R132S; and 2.4% (3/124) had an IDH2 mutation, of which 2 cases had a mutation at site 172 (R172W, R172K), and 1 case had a mutation at site 174 (A174Y)." (PMID 32146731, 2020). "Recent comprehensive genomic profiling has greatly elucidated the molecular hallmarks of gliomas, including the mutations in isocitrate dehydrogenase 1 and 2 (IDH1 and IDH2), loss of chromosomes 1p and 19q (1p/19q), and epidermal growth factor receptor variant III (EGFRvIII)." (PMID 33521638, 2020). "Mutation in IDH2 occurs in only 4% of GBM cases and in II–III grade gliomas." (PMID 32392704, 2020). "Also, there are only very few high-frequency mutated driver genes like IDH1/IDH2 and promoter of TERT discovered in gliomas." (PMID 32328184, 2020). "IDH1 and IDH2 have been reported to be mutated in 70% of grade II and III gliomas and glioblastomas, as well as in angio-immunoblastic T-cell lymphomas, acute myeloid leukemia (AML) and other common cancer types, such as thyroid, colorectal and prostate cancers." (PMID 32548570, 2020). "IDH2 mutations are found in AITL, myeloid tumors, and gliomas." (PMID 32796826, 2020). "Mutations of IDH1 and IDH2 have been recognized as oncogenic events through decreasing α-ketoglutarate and increasing D-2-hydroxyglutarate production, and the neomorphic IDH mutant has been shown in acute myeloid leukemia and gliomas." (PMID 32509584, 2020). "IDH1 and IDH2 mutations in AML are mutually exclusive, as in glioma." (PMID 31165048, 2019). "IDH2 mutant gliomas have a higher level of 2-HG/tCho (total choline=phosphocholine+glycerylphosphorylcholine) (2.48 ± 1.01vs.0.72 ± 0.38, Pc < 0.001) and myo-Inositol/tCho (2.70 ± 0.90 vs. 1.46 ± 0.51, Pc = 0.011) compared to IDH1 mutation gliomas." (PMID 30791611, 2019). "In 2009, IDH1/IDH2 was found to be a good prognostic factor for low-grade gliomas." (PMID 32038995, 2019). "And although IDH1 and IDH2 mutations are frequent in human gliomas, they are not a consistent or common feature of the canine condition." (PMID 31824863, 2019). "In gliomas, mutations of the cytosolic IDH1, most frequently occurring heterozygous IDH1 R132H point mutation, are much more common than mutations of the mitochondrial homolog IDH2." (PMID 31652645, 2019). "Of all gliomas, IDH1 revealed a higher mutation rate than IDH2." (PMID 31450822, 2019). "IDH1/R132 and IDH2/R172 are commonly found in gliomas, cholangiocarcinomas, and chondrosarcomas, with a higher frequency of IDH1/R132 mutation occurring in these cancers (58%–90%, 40%–50%, and 50%–60% respectively) compared to IDH2/R172 (3%–5%, 5%–10%, and 10%)." (PMID 31817761, 2019). "In gliomas, depending on the tumor histopathology and the patient’s clinical features, this integrated diagnosis may require assessing the tumor for IDH1 and IDH2 (IDH), H3F3A, and BRAF mutations, as well as the 1p/19q codeletion." (PMID 31167453, 2019). "To refine the diagnostic accuracy, we use Sanger sequencing, for example to detect rarer mutations in the IDH1, or IDH2 genes, histones, or to detect mutations in the TERT promoter either to support glioma diagnostics in the context of other mutations or to prognosticate meningioma recurrence risk." (PMID 30786920, 2019). "Our results suggest that UHF 1H MRS could be useful as a prognostic precision medicine biomarker detection system for identifying, stratifying, and monitoring IDH1 and IDH2 mutant glioma patients towards the goal of precision medicine of gliomas." (PMID 30791611, 2019).
glioma (continued). "Furthermore, our data indicates that the myo-Inositol/tCho metabolite ratio is higher in mitochondrial IDH2 gliomas compared to cytosolic IDH1 gliomas." (PMID 30791611, 2019). "Our results suggest that 1H MRS could be useful as a prognostic precision medicine biomarker detection system for identifying, stratifying, and monitoring IDH1 and IDH2 mutant glioma patients." (PMID 30791611, 2019). "To assess whether GNA13 might facilitate similar processes in ATRX-deficient human disease, we examined TCGA gene expression data for lower-grade glioma (LGG), focusing our analysis on those tumors harboring an IDH1 or IDH2 mutation." (PMID 29535300, 2018). "Recently, some cases of gliomas have been found to be associated with somatic mutations in the gene encoding isocitrate dehydrogenases (IDH) 1/2, with point mutations at highly conserved residues in the active sites of IDH1 (e.g. R132H) and IDH2 (e.g. R172K)." (PMID 30192797, 2018). "The importance of glioma molecular profiling was underscored by the WHO in 2016, when it issued a new glioma classification based on certain mutations in the genes coding for isocitrate dehydrogenases (IDH1, IDH2) and 1p/19q codeletion." (PMID 31435515, 2018). "The dual target inhibitor of mutant IDH1 and mutant IDH2, AG-881, is an orally available inhibitor that can pass the blood-brain barrier and may serve as a better option for glioma patients." (PMID 28748451, 2018). "A longer survival is observed in patients with gliomas harboring the presence of IDH1 or IDH2 mutations, whereas the absence of IDH1 appears as a strong predictor for poor prognosis." (PMID 29953478, 2018). "The 2016 CNS WHO criteria state that, for a complete diagnosis of the types of adult glioma, analysis for specific mutations of the two genes, IDH1 and IDH2 (IDH), which encode isocitrate dehydrogenase 1 and 2, respectively, and of chromosome 1p/19q codeletion status, is essential." (PMID 28915660, 2017). "70–90 % of grades II and III glioma and secondary GBMs carry mutated IDH1 or IDH2 genes." (PMID 27752843, 2017). "Subsequently, it has been shown that >75% of low-grade gliomas and 20% of AML have mutations in IDH1 or IDH2, and mutations are also found in other solid tumors such as chondrosarcoma, cholangiocarcinoma, colon, pancreatic and prostate cancer to varying extents." (PMID 28986582, 2017). "In addition, overexpression of mutant IDH2 (R172G) in glioma cells induces nuclear accumulation of β-catenin and upregulation of HIF-1α (hypoxia-inducible factor-1α) signaling that were closely related with tumor invasion and chemoresistance." (PMID 29207533, 2017). "IDH1 and IDH2 mutations have been identified in ∼15–20% of AML and glioma patients." (PMID 29290954, 2017). "Therefore, 2HG can be used as a specific Magnetic Resonance Biomarker, monitoring IDH1 and IDH2, tracking glioma state and identifying the boundary between tumor and normal tissue." (PMID 28939851, 2017). "Our aim was to provide insight into the differences between IDH1 and IDH2 mutant gliomas." (PMID 27245697, 2016). "IDH2 mutations were found in 0.5 % of pGBM (1/215), 3.4 % of sGBM (1/29) and 2.8 % (16/577) of low grade gliomas, while IDH1 mutations are found in 14.1 % (29/205) of pGBM, 55.2 % (16/29) of sGBM and 69.8 % (403/577) of low grade gliomas." (PMID 27245697, 2016). "Among 196 glial tumors with nuclear ATRX loss, 173 (89 %) had an IDH1 or IDH2 mutation." (PMID 27311324, 2016). "In addition, whole-transcriptome sequencing and DNA methylation data were used to assess the distribution of genetic changes in IDH1 and IDH2 mutant gliomas in a Chinese population-based cohort." (PMID 27245697, 2016). "Understanding the underlying biology of the differences in outcome observed for IDH1 and IDH2 mutant gliomas will be important for future studies and may lead to the development of novel approaches to therapy." (PMID 27245697, 2016).
glioma (continued). "Mutant IDH1 and IDH2 alter glioma metabolism, favoring the reduction of α-ketoglutarate to 2-hydroxyglutarate (2-HG), which in turn inhibits DNA and histone demethylases and establishes a glioma-CpG island hypermethylator phenotype (G-CIMP), featuring hypermethylation at a large number of loci." (PMID 25785247, 2015). "Detection of molecular glioma biomarkers such as MGMT promoter methylation, IDH1/IDH2 mutation, 1p/19q co-deletion, epidermal growth factor receptor (EGFR) amplification and EGFR variant III (EGFRvIII) expression in tumor tissue is increasingly being used in clinical care." (PMID 25720744, 2015). "IDH1 and IDH2 genes have become a focus for research aimed at understanding the biology of gliomas." (PMID 26220714, 2015). "Curiously, although IDH1 and IDH2 mutations are clearly powerful drivers of low grade glioma and AML, they seem to be rare or absent in other tumor types." (PMID 25232952, 2014). "Similarly, as IDH2 inhibitors currently in trial for hematologic malignancies open for glioma patients, sequencing remains the only method of identifying eligible patients." (PMID 25257301, 2014). "Mutations in the IDH2 gene have been detected in up to 3% of glial tumours WHO grades II and III but not in GBM." (PMID 24868540, 2014). "An alternative manner to deal with decreased cytosolic α-KG, apart from increasing IDH2 activity, may be increased import of glutamine via specific importers in glioma cells." (PMID 24252742, 2013). "We have shown consistent IDH1/IDH2 status in the progression of gliomas and lack of association between IDH1mutation and malignant progression." (PMID 23840696, 2013). "A significant proportion of low grade gliomas (>85%) and a smaller proportion of glioblastomas contain mutations in IDH1 or IDH2, which have been shown to associate with a specific hypermethylated phenotype and predict better overall survival for those patients." (PMID 24202321, 2013). "Heterozygous mutations in IDH2 at Arg172 and at the analogous residue Arg132 in IDH1 are frequently found in grade 2 and 3 gliomas, secondary glioblastomas, and acute myeloid leukemia (AML), but they occur less frequently in primary glioblastomas and other cancers." (PMID 22675360, 2012). "Moreover, whereas mutations in SDH and FH occur throughout the gene, the majority of IDH mutations identified in gliomas and AML are changes in the amino acid residues R132 in IDH1 and either R172 or R140 in IDH2." (PMID 22888353, 2012). "Twenty five IDH1 mutations were present in the gliomas tested (23 × R132H, 1 × R132S, and 1 × R132L); no IDH2-mutant tumors were present." (PMID 23267435, 2012). "R172K, R172M, and R172G are the IDH2 substitions observed in gliomas." (PMID 21326614, 2011). "In the vast majority of IDH mutated gliomas (>90%), these mutations are located at codon 132 of IDH1 and result in an arginine-to-histidine (R132H) substitution at the active site, although other mutations affecting the corresponding arginine residue in IDH1 or IDH2 have been described as well." (PMID 39203017, 2024). "Furthermore, the Idh1 and Idh2 mutations identified in rat gliomas did not have homology to known human variants in COSMIC database." (PMID 38232086, 2024). "In addition, the fact that IDH2 mutations are less abundant in gliomas did not lead to many clinical studies on glial tumours." (PMID 37296846, 2023). "In this study, IDH1 gene mutation was detected in 86 cases (74.8%), IDH2 gene mutation in five cases (4.4%) and TERT promoter mutation in 68 cases (59.1%), the results showed that IDH1/2 and TERT genes were related factors affecting the prognosis of patients with glioma." (PMID 37250582, 2023). "Furthermore, various animal models with IDH1 or IDH2 mutation recapitulated neurodegeneration, but not glioma genesis despite the epigenetic and transcriptomic resemblance." (PMID 35203456, 2022).
glioma (continued). "A novel variant in EZHIP and an IDH2 variant never reported in gliomas were documented." (PMID 35456430, 2022). "Furthermore, we called single nucleotide variants to confirm that mutations of the IDH1 and IDH2 genes, which are mutated in about 10% of human high-grade gliomas, had not spontaneously occurred during in vivo passaging and tumor development." (PMID 33435218, 2021). "Furthermore, mutations in the IDH2 gene (encoding a mitochondrial NADP+-dependent enzyme) at the analogous Arg172 were relatively uncommon in lower-grade glioma and non-existent in glioblastoma." (PMID 34440884, 2021). "The therapeutic efficacy in IDH2 mutated glioma has not yet been determined." (PMID 34571995, 2021). "Second, despite the IDH1R132H mutation being the most influential genetic factor for postoperative oncological outcomes of gliomas, information concerning other potential factors such as the chromosomal 1p/19q codeletion, IDH2 or MGMT mutation, and ATRX mutation was not considered." (PMID 34389754, 2021). "Specific cancer cells, notably grade II/III glioma, secondary glioblastoma, and acute myeloid leukemia (AML) cells, exhibit heterozygous point mutations in the active sites of cytosolic isocitrate dehydrogenase isoform 1 (IDH1) or isoform 2 (IDH2), localized in the mitochondrial matrix." (PMID 31847543, 2020). "For example, on the basis of mutations in the genes encoding the isocitrate dehydrogenases IDH1 and IDH2, co-deletion of 1p19q (oligodendroglioma) and methylation of O6-Methylguanine-DNA methyltransferase (MGMT) have been subclassified as molecular diagnostics and prognostic markers for gliomas." (PMID 33228738, 2020). "Therefore, we focus exclusively on the roles of IDH1 and IDH2 in glioma biology in this article." (PMID 31263678, 2019). "While we could provide evidence that XAF1 methylation is strictly (100%) linked to 2-HG-producing mutations in IDH1 (shown for R132H, R132G) in grade III gliomas, we were not able to identify a less frequent IDH2-mutant tumor within the data set." (PMID 28122345, 2017). "Indeed, those genes are important prognostic factors in glioma patients; in particular, IDH1 and IDH2 can be mutated in low-grade and anaplastic glioma, as well; in fact, mutations of IDH1 and IDH2 genes are found in 70% of grades II and III gliomas and secondary glioblastomas." (PMID 27493954, 2016). "Moreover, MsMab-1 reacted with IDH2-R172G, which was reported in gliomas." (PMID 24403254, 2013). "Nevertheless, the existence of exclusively heterozygous IDH2 (and IDH1) mutations in gliomas and AML and the small possibility of dominant-negative mutations (minor mutant fractions existing could not exert this role) have led to the search for other consequences of IDH1 and IDH2 mutations." (PMID 22675360, 2012). "However, it is unclear whether binding to IDH1-WT or IDH2-WT is shared by all of the glioma-derived IDH mutants, or whether IDH mutants actually bind a significant portion of IDH1-WT or IDH2-WT molecules to exert this dominant negative function in cells." (PMID 21326614, 2011). "In contrast to this, all of these mutants confer 10- to 100-fold higher 2HG production to cells, and glioma tissues containing IDH1 R132 or IDH2 R172 mutations contain high levels of 2HG compared to glioma tissues without IDH mutations (54.4 vs. 0.1 mg 2HG/g protein)." (PMID 21326614, 2011). "FDA-approved drugs such as ivosidenib and enasidenib, which target IDH1 and IDH2 respectively, have shown clinical efficacy in treating IDH-mutant AML, glioma, and cholangiocarcinoma, both as monotherapies and in combination therapies." (PMID 40641934, 2025).